KIAA0232 (KIAA0232)
Tractability: PROTAC: ubiquitination databases record sites on it.
Gene: Protein-coding gene on chromosome 4 (6,781,375 to 6,884,170, forward strand). Ensembl gene ENSG00000170871.
Subcellular location (Human Protein Atlas): Cytosol; Cell Junctions; Mitochondria
Gene Ontology:
Molecular function: protein binding
Genetic constraint (gnomAD): Loss-of-function variants: 23 observed, 108.69 expected, observed/expected ratio (o/e) 0.21, 90% interval 0.15 to 0.3. The upper end of that interval is the gene's LOEUF score, 0.3, which puts it in group 1 of 6, group 1 being the genes least tolerant of losing a copy. Missense variants: 1,435 observed, 1,597.5 expected, observed/expected ratio (o/e) 0.9, 90% interval 0.86 to 0.94. Synonymous variants: 576 observed, 576.72 expected, observed/expected ratio (o/e) 1, 90% interval 0.93 to 1.07.
Homologues: Orthologues: chimpanzee KIAA0232 (99% identical), macaque KIAA0232 (99% identical), rat Kiaa0232 (89% identical), mouse D5Ertd579e (89% identical), guinea pig KIAA0232 (88% identical), dog KIAA0232 (88% identical), rabbit KIAA0232 (83% identical), tropical clawed frog KIAA0232 (63% identical), zebrafish kiaa0232 (55% identical).
Diseases named in the same sentence as KIAA0232 in open-access papers:
KIAA0232 is named in the same sentence as 1 disease in open-access papers, as found by Europe PMC text mining. Sharing a sentence is not in itself a finding about the gene and the disease. The quoted sentences say what the papers report.
cancer (1 paper, 2023). A tumor composed of atypical neoplastic, often pleomorphic cells that invade other tissues. "Genes related to rs117719091 (PFKFB3) and rs140233124 (KIAA0232) play crucial roles in cancer metabolism; PFKFB3 induces glycolysis and activates hepatic stellate cells and then promotes liver fibrosis, and KIAA0232 stimulates insulin secretion to regulate cancer metabolism." (PMID 38003606, 2023). "For group 1, seven of the thirteen novel-loci-related coding or noncoding genes, namely F11/F11-AS1, PFKFB3, PRMT8, FAM66C, NAV2/NAV2-AS1, FRMD4A, and KIAA0232, have been demonstrated to be correlated with the development of HCC or other cancers in many studies." (PMID 38003606, 2023).